IRF3 (interferon regulatory factor 3)
Diseases named in the same sentence as IRF3 in open-access papers (continued):
Sharing a sentence is not in itself a finding about the gene and the disease.
infection (continued). "According to the model, the fraction of cells that display both RSV proteins and IRF3 activity increases in time (as the infection progresses) and substantially decreases with the strength of inhibition of pIRF3 by vProteins (left subpanel)." (PMID 37669278, 2023). "TOB1 interacted with IRF3 following infection with Sendai virus (SeV, an ssRNA virus recognized by RIG-I), vesicular stomatitis virus (VSV, another ssRNA virus recognized by RIG-I), or lipopolysaccharide (LPS; a Toll-like receptor 4 ligand)." (PMID 36085336, 2022). "Yap+/- mice showed increased Ifnb1 and Irf3 expression in both mRNA and protein levels upon infection, which is in support of our in vitro results." (PMID 35503798, 2022). "Interferon (IFN) regulatory factor 3 (IRF3)-dependent signalling is crucial for pathogen clearance and host survival in response to infection by many viral and bacterial pathogens." (PMID 35215908, 2022). "Crucially, after both 3p-hpRNA transfection and infection with PR8 R38K41A IAV at an MOI of 15 the levels of IRF-3 phosphorylation were similar in WT and TRIM25 KD cells." (PMID 35736141, 2022). "The translocation of IRF3 to the nucleus was found to be greater in Prmt9CKO macrophages than that of Prmt9WT macrophages after infection with SeV." (PMID 36028484, 2022). "Some interferon regulatory factors (irf1, irf3, irf4b, irf5, irf6, irf8) continued to show upregulation during the later stages of infection (day 6 to day 10) in virus-infected fish spleens." (PMID 36016951, 2022). "Compared with control PBS and oncoVV infection, the transcription activities of IRF-3 and AP-1 in oncoVV-AVL group were significantly upregulated." (PMID 35736181, 2022). "Because TBK1 mediates the phosphorylation and nuclear transcription of IRF3 during infection, we also examined activation of IRF3." (PMID 36044516, 2022). "Upon infection, lncRNA-ISIR, an IRF3-binding lncRNA, is induced by IFN-I, which associates with IRF3 to prevent Fli-1 binding with IRF3, thus facilitating IRF3 activation." (PMID 36189363, 2022). "We found that the levels of phosphorylation of TBK1, IRF3 and IκBα were higher in Prmt9CKO macrophages than those of Prmt9WT macrophages after infection with SeV or stimulation with 5’ppp-RNA." (PMID 36028484, 2022). "At 2, 4, and 6 hpi, HSV-2 SD90e Δ21 infection also displayed significantly more cells with nuclear IRF-3 compared to WT." (PMID 36374856, 2022). "RIG-I and MDA5 can sense RNA virus genomes directly, but also RNA generated by infection with DNA viruses, leading to IRF3 and NF-κB activation." (PMID 35148361, 2022). "Deficiency of Yap in mice also resulted in transcriptional upregulation of Tlr3, and elevated activation of Irf3 signaling in lung tissue upon infection, which was accompanied by a reduction in viral nucleocapsid (NP) protein expression upon infection." (PMID 35503798, 2022). "Consistently, measuring IRF3 nuclear translocation by single-cell immunofluorescence showed reduced activation of IRF3 after infection with Alpha compared to infection with VIC." (PMID 34942634, 2022). "As expected, phosphorylation of IRF3 at serine 386 was induced upon infection of the control cells at both analyzed time points (lanes 2 and 3)." (PMID 35939517, 2022). "IRF3, interferon regulatory factor 3, a tumor suppressor, plays an important role in inhibiting infection and cancer." (PMID 35127830, 2022). "We found that phosphorylation of IRF3 in TRIM18 KO BMDM was enhanced relative to WT BMDM after infection with CVB3 or adenovirus." (PMID 35909127, 2022). "After infection of target cells, RNA viruses trigger the activation of downstream IRF3 and IRF7 and NF-κB transcription factors and the production of IFNs." (PMID 35663932, 2022). "A day later the pathways were activated by infection with SeV (for IRF3), or addition of IFN-α (for ISRE) or TNF-α (for NF-κB) and the luciferase activity was measured compared to empty vector (EV) control." (PMID 36478862, 2022).
infection (continued). "This study found that DDX50 was required for optimal IRF3/NF-κB-dependent gene expression, and cytokine synthesis and secretion following stimulation with dsRNA, SeV infection, or infection with the dsDNA viruses HSV-1 and VACV." (PMID 35215908, 2022). "When triggered by an infection, interferon regulatory factor 3 (IRF3) is phosphorylated to form a homodimer." (PMID 36232610, 2022). "At 2, 4, and 6 hpi, HSV-1 F and KOS Δ21 infections had significantly more cells with nuclear IRF-3 compared to their respective WT infections." (PMID 36374856, 2022). "This is consistent with the phosphorylation of TBK1 and IRF3 within 30–60 min post infection following the activation of TLR4-TRAM-TRIF signaling." (PMID 35947948, 2022). "Upon infection with Sendai virus (SeV), a single-stranded RNA virus, Otud1−/−-MEFs and -BMDMs showed reduced expression of IRF3-target genes as compared to Otud1+/+-cells." (PMID 35941131, 2022). "On examination of downstream signaling events, interferon (IFN) regulatory factor 3 and IFN regulatory factor 7 (IRF3−/− IRF7−/−) double knockout (DKO) mice experienced lethal infection; whereas, individually, the IRF3 and IRF7 KO models showed >90% survival." (PMID 35301331, 2022). "At 16 hrs p.i., ΔM062R infection continues to stimulate the phosphorylation of IRF3 to higher levels than that by the wildtype MYXV." (PMID 36103568, 2022). "We found that pre-exposure to PS-NH2 significantly reduced mpo, il8, and irf3 transcription upon infection compared with NP-unexposed but NNV-infected cells, while exposure to PS-COOH decreased and increased that of mpo and il1b, respectively." (PMID 35163406, 2022). "In our study, MAPK20 and IRF3 were significantly up-regulated by HN10 infection, suggesting their important roles in receptor signal transduction." (PMID 35893682, 2022). "We next confirmed the phosphorylation of IRF3 during ΔM062R infection that was detected as early as 4 hours (hrs) post-infection (p.i.)and persisted at 8 hrs p.i.." (PMID 36103568, 2022). "There was little change in the expression of IRF3 during the course of the infection, but these other genes were expressed at ca. 5–10-fold elevated levels at 6 dpi compared to 0 dpi." (PMID 36298701, 2022). "Of note, at 8 h post infection, SeV substantially stimulated phosphorylation of IRF3, a downstream protein for both RLR-MAVS and cGAS-STING pathways." (PMID 34732709, 2021). "Nlrp12−/− BMDCs had increased TBK1 and IRF3 phosphorylation concomitant with increased production of type I IFNs upon infection with VSV or short dsRNA compared to WT cells." (PMID 33808506, 2021). "Both WT VK2 and TRIM26 KO cell lines showed significant increase in HSV-2 GFP infection after BX-795 treatment, a result that confirms that inhibition of the IRF3 pathways contributes to increased HSV-2 infection." (PMID 33419081, 2021). "Following infection, IRF3 and IRF7 are phosphorylated by the virus-activated kinase components, IKKε and TBK1." (PMID 34440891, 2021). "In SARS-CoV-2-infected cells, there was a significant increase in IRF3 expression 24 h post-infection, and of NF-κB 48 h post-infection, which was maintained until 72 h post-infection." (PMID 34576716, 2021). "Both NF-κB and IRF3 presented an increased phosphorylation 48 h post-infection (p < 0.001; Student’s t-test)." (PMID 34576716, 2021). "Deficiency in IRF7, which is activated similar to IRF3, has also been connected with the susceptibility to SARS-CoV-2 and IAV infections in humans." (PMID 33805458, 2021). "The amount of nuclear-translocated IRF3 was obviously increased following ASFV-Δ7R infection compared with that of ASFV-WT infection." (PMID 34310655, 2021). "WNV induces IRF3 activation approximately 12–16 h post infection, in contrast to an assortment of other viruses which induce IRF3 within 3–10 h post infection suggesting WNV delays initiation of the host response." (PMID 33498715, 2021).
infection (continued). "We found that CAP reduced the enhanced level of IRF3/7 on IBRV infection while increasing IRF3/7 in normal cells." (PMID 33554733, 2021). "IRF3 expression diminished with IRF3 phosphorylation at 4 h post-infection of SeV in JMJD6-overexpressing HEK293T cell lines." (PMID 33684176, 2021). "PUUV and TULV NSs proteins have already been shown to be expressed during infection and to inhibit NF-κB- and IRF-3-responsive promoters after poly(I:C) stimulation." (PMID 34389893, 2021). "Of note, the levels of phosphorylation of IRF3 and IRF7 in U937 cells infected with m6A-deficient HIV-1 were 2.6- and 3.1-fold higher than those in mock infection, and 1.6- to 1.7-fold higher compared to cells infected with control HIV-1." (PMID 33690734, 2021). "Virulent VACV strains inhibits STING dimerization and phosphorylation during infection, efficiently suppressing DNA sensing and IRF-3 activation." (PMID 35096660, 2021). "Infection of WT cells leads to IRF3 activation and pIRF3 location in the nucleus as expected, but this does not occur in TRIM26 OE cells and is exaggerated in the response of TRIM26 KO cells." (PMID 33419081, 2021). "Decreased TBK1 activity in B.1.1.7 infection also suggests potent antagonism upstream of IRF3 by additional mechanisms." (PMID 34127972, 2021). "Specifically, early in the infection (6 h post-infection) the activation of IRF3 promotes IFN-I and subsequently ISGs production." (PMID 34361973, 2021). "Later in the infection, IRF3/BAX-mediated activation of intrinsic apoptotic pathway releases the PI3K/AKT-mediated inhibition of RIPA." (PMID 33805458, 2021). "Possibly, the increase in IL-1β mRNA levels induced by IRF-3 expression is mediated indirectly and only upon infection with a cytoplasmic DNA virus VACV, as suggested by the modest stimulatory effects of WR-Luc." (PMID 34696416, 2021). "(I) Quantification of EMCV 5′UTR 24 hr post EMCV infection (MOI=0.001) in WT or IRF3 KO 293FT cells transfected with a control EV, p42, or p46." (PMID 34342578, 2021). "Consistently, measuring IRF3 nuclear translocation by single-cell immunofluorescence demonstrated reduced IRF3 activation after B.1.1.7 infection compared to VIC." (PMID 34127972, 2021). "HS and ST infection alone decreased the protein expression of IRF3 (P<0.05 and P<0.05, respectively) in the jejunum of broilers compared with control group broilers." (PMID 34061266, 2021). "IRF3 activation was also virus dose‐dependent but did not maximise until 72 hpi, later than NF‐κB, and we observed a more modest shift in IRF3 nuclear intensity compared with NF‐κB throughout infection." (PMID 34101213, 2021). "IRF3 tail is also strongly targeted for post-translational modifications upon infection, leading to its homodimerization (PDB: 1QWT), translocation into the nucleus and transcriptional activation." (PMID 33372854, 2021). "Activated IFI16 induced the expression of IFNβ through IRF3 activation and the production of NF-κB-dependent proinflammatory genes during infection with several DNA viruses, including HIV, HSV-1, and VACV." (PMID 34356829, 2021). "Infection with the bacterial pathogen such as mycobacterium tuberculosis can trigger cGAS and then stimulate IRF3-dependent type I interferon response." (PMID 34016129, 2021). "In this study, we provide evidences that T. gondii requires activation of host TBK1/IRF3 and downstream genes (ISGs) expression for its efficient infection and growth in ARPE‐19 cells." (PMID 34464509, 2021). "vSlfn-deficient ECTV was strongly attenuated in mouse infection models and unable to block the activation of STING, TBK1, and IRF3 in macrophages and correlated with a strong IFN response." (PMID 34356829, 2021). "In this research, we found that influenza virus A/FM/1/47 (H1N1) infection and Poly I:C contribute to the activation of IRF3." (PMID 34497658, 2021).
infection (continued). "The removal of up to three key genes (C10L, N2L, and C6L) from VACV did not reduce the strength of viral replication, both in vitro and in vivo, but resulted in the rescue of IRF3 phosphorylation upon infection of cancer cells." (PMID 34553028, 2021). "In contrast, IRF3 phosphorylation was weakly stimulated after SARS-CoV-2 infection at 8 h, while it was sharply increased after infection at 16 h; the kinetic of IRF3 phosphorylation is consistent with that of STING phosphorylation." (PMID 34732709, 2021). "Accordingly, knock-down of TRAIP in primary peritoneal macrophages increased IRF3 activation upon infection with SeV, consistent with increased IFNβ production resulting from increased TBK1 activity." (PMID 33808506, 2021). "Of these, IRF3 is considered important for non-immune cells because a number of cell populations that express IRF3 in the steady state, are upregulated by infection." (PMID 34389779, 2021). "TLRs transduce the infection signal through MAPKs, NF-κB, and IRF3, which induce the transcription of proinflammatory cytokines and type I interferon." (PMID 34001091, 2021). "The transcription factor IRF3 is glutathionylated in uninfected cells, but upon infection by the Sendai virus, GRX-1 mediates the deglutathionylation of IRF3." (PMID 33805458, 2021). "But, in response to the pathogens infection, IRF3 can be activated by phosphorylation of the C‐terminal region at seven Ser/Thr residues (Ser385, Ser386, Ser396, Ser398, Ser402, Ser405 and Thr404)." (PMID 34464509, 2021). "It was found that DNA-induced activation of STING and IRF3 can be inhibited by infection with cowpox virus, ECTV, and VACV strains Copenhagen (COP) and Western Reserve (WR), but not by MVA." (PMID 34356829, 2021). "This is consistent with the observation that Irf3−/− mice demonstrated a more severe decrease in early liver ISG induction compared to Irf7−/− mice following P. berghei (ANKA) infection." (PMID 33408718, 2020). "Only at high levels of IRF3 activity, i.e., at the peak of activity later in infection or brought about by expression of the constitutively active IRF3-S396D, p50-p65 is dispensable for IFNB1 transcription." (PMID 32645843, 2020). "In contrast, we found, enhanced productive infection of DCs exposed to HIV-C also increases IRF3 activation and phosphorylation of TBK1 only in WT-THP1-DCs and CD11b KO THP1-DCs, but not CD11c KO THP1-DCs." (PMID 32922405, 2020). "When type I IFN levels were assessed in IRF3 or IRF7 knockout mouse models at later stages of infection (5 days post infection), significantly higher levels of IFN were produced compared to wild type." (PMID 32708188, 2020). "Because TBK1 has been implicated in autophagy induction, whereas IRF3 acts as a transcription factor to induce type I IFNs downstream of STING, we investigated the role of these proteins in the context of an in vivo infection with HSV-1." (PMID 32636381, 2020). "RIG-I activation by 5′ppp-RNA stimulates the production of IFNβ from lung epithelial cells to the same extent as monocytic cells, albeit very late after infection at 48–72 h, through IRF3 and STAT1 activation." (PMID 32541772, 2020). "Taken together, these results suggest that individual members of the PC have both distinct and complementary abilities to directly modulate NF-κB and IRF3 signaling with the net result being blockade of NF-κB and IRF3 signaling in both models of infection." (PMID 32393794, 2020). "Cellular sensing of initial HPV infection has not been formally investigated, but several studies have described roles for the early HPV oncogenes in antagonizing the cGAS/STING/IRF3 axis following establishment of infection." (PMID 33253291, 2020). "Cells were then immunostained for bRSV F as a marker for infection as well as for the NF-κB subunit p65 or, separately, IRF3." (PMID 32878896, 2020).
infection (continued). "As anticipated, we saw a cell type dependent increase in all three transcription factors when cells were treated with poly I:C and a significant increase in phospho-IRF3 was seen in all cell types of the model of ascending infection." (PMID 32983111, 2020). "Overexpression of CiNEK6 notably reduced cell viability and impeded the protective effect of IRF3 on the cells under infection with GCRV." (PMID 33488591, 2020). "As before, HPV infection did not activate the pathway as detected by phosphorylation of STING or IRF3 during infection." (PMID 33253291, 2020). "Upon infection, phosphorylation of the AIE and accompanying structural rearrangements enable IRF3 to associate with CBP, and this interaction retains the activated holocomplex in the nucleus." (PMID 32645843, 2020). "A minimal increase in mycobacterial burden was detected in Mavs–/–BMMs as well as RIG-I, TBK1, IRF3 or IRF7-knockdown BMMs when compared to WT or control siRNA-treated cells at 72 hr post infection." (PMID 32463840, 2020). "Loss of Banf1 expression was associated with reduced infection of RNA and DNA viruses, and the enhanced expression of ISGs was mediated by a pathway requiring cGAS, STING, and IRF3." (PMID 32156810, 2020). "Deletion of the entire vSchlafen or only its cGAMP nuclease domain in the context of ECTV renders the virus unable to suppress IRF3 activation during infection and leads to a dramatic 5-log drop in virulence in mice, the natural host of ECTV." (PMID 33117352, 2020). "Deletion of IRF3, stable expression of Npro, and infection with wild-type CSFV were found to antagonize the mitochondrial localization of Bax, a key hallmark of the intrinsic, mitochondrial pathway of apoptosis." (PMID 33328306, 2020). "This shifts the control of gene expression in fibroblasts, epithelial and endothelial cells from IRF3-mediated regulation upon initial sensing of an infection towards IRF7-mediated in later phases." (PMID 32645843, 2020). "They found that the virulent Copenhagen and Western Reserve VACV strains inhibited STING dimerization and phosphorylation during infection and in response to transfected DNA and cGAMP, thus effectively inhibiting DNA sensing and the activation of IRF3." (PMID 32983084, 2020). "Results obtained showed that AiV infection induced a low level of RIG-I/IRF3 and LC3/p62 signaling activation, resulting in a low level of type I IFN production, and implying downregulation of RLR signaling by AiV for its replication." (PMID 32802187, 2020). "In order to focus only on infected cells, we immunostained HBc as an infection marker, and analyzed IRF3 nuclear translocation after HT-DNA transfection." (PMID 32485908, 2020). "In line with the results obtained from the infection analyses, we detected that the p-IRF3 signaling is significantly disrupted upon CD11c KO, but intact in WT- and CD11b KO-THP1 DCs." (PMID 32922405, 2020). "At early time point, 12 and 24 h post JEV infection, the p-AKT/AKT and p-IRF3/IRF3 proteins were shown to be up-regulated, whereas at later stages of the infection progress (at 48 h), the expression of p-AKT/AKT and p-IRF3/IRF3 have shown the decreasing trend." (PMID 31448245, 2019). "GzmA levels peaked on day 2 post infection, reaching high levels (range ≈500–3,000 pg/ml) that were on average ≈7 fold higher in IRF3/7−/−mice than those seen in wild-type mice." (PMID 31993061, 2019). "P/V-CPI- infection induced phosphorylation of IRF-3 (lane 3), consistent with strong induction of IFN-β synthesis." (PMID 31083335, 2019). "This demonstrates that—after initial moderate activation—virulent Armenia/07 is able to inhibit STING and IRF3 phosphorylation at later time points after infection; similar results were observed in regard to IFN-β synthesis." (PMID 30918080, 2019). "The arrow points to a cell in the late stages of infection, in which IRF3 is aggregated in the nuclear periphery." (PMID 31090537, 2019).